IL2 (interleukin 2)
Diseases named in the same sentence as IL2 in open-access papers (continued):
Sharing a sentence is not in itself a finding about the gene and the disease.
viral infection (continued). "Remarkably, the severe depletion of IL-2-secreting T cells was confined to those specific for T. cruzi, as higher frequencies of IL-2-secreting CD8+ T cells specific for influenza, a viral infection associated with antigen clearance, was found in these patients." (PMID 18846233, 2008). "A biological approach that caused excitement was that Treg could be expanded using immune complexes of IL-2 and mAb (clone JES6-1) to IL-2, but reports of its success to limit an inflammatory reaction caused by a viral infection are not available." (PMID 37671156, 2023). "Notably, current pathological studies have shown that the severe patients infected by SARS-CoV-2 generally have higher plasma levels of IL-2, IL-6, IL-10, TNF-α, IFN-γ,41,43–45 implying a high risk of the inflammatory-associated cytokine storm after viral infection." (PMID 33895786, 2021). "That study found that there was a significant difference between NK cells with sufficient Treg and those in Treg-depleted mice after viral infection, and the Treg-mediated inhibition effect on NK cells may be exceeded by the immune effect of high levels of IL-2 during virus infection." (PMID 33013198, 2020). "Thus, inflammatory signals induced by viral infection may overcome the need for strong IL-2 signals in driving cytotoxicity in CD4 cells." (PMID 24586481, 2014). "Immune activation against viral infections involves the typical responses of specific cytokines such as IFN-γ, IL-2, and IL-4." (PMID 39507777, 2024). "To illustrate, the viral infection results in CD8+ T-lymphocytosis, releasing a pool of cytokines, including interferon-gamma, interleukin-2, and TNF-alpha." (PMID 38883093, 2024). "Th1 cells also regulate the differentiation of CD8+ T cells through IL-2 and IFN-γ secretion to clear viral infection." (PMID 39066362, 2024). "IL-10 inhibits the production of key cytokines such as IL-2 and interferon-γ (IFN-γ) by T helper type 1 (Th1) cells, which are essential for the control of viral infections." (PMID 39459871, 2024). "During acute viral infection, IL6 activates both Stat1 and Stat3, with the latter being required to limit IL2/Stat5-induced Th1 differentiation." (PMID 37275873, 2023). "In T cell exhaustion, loss of individual effector molecules follows the hierarchical order of IL-2, TNF-α, IFN-γ, and proliferation during the establishment of chronic viral infection." (PMID 35040433, 2022). "This overlap occurs within several pathways: IL2 (IL2), BCR signaling (BLK, Lyn etc.), tolerance response to nucleic acid (CD72, TLR7), tolerance to self-nucleic acid and control of viral infection." (PMID 36090990, 2022). "The differential genes such as KITLG, FOXP3, miR-451, IL-2, IL-10, IL-6, and TNF-α are mainly involved in viral infection and the immune-inflammatory responses." (PMID 34867371, 2021). "In the context of a viral infection, the combination of IFN-γ and IL-2 would induce the activation of effector T cells with pro-inflammatory properties and the capacity of generating an effective immune response to eliminate the virus." (PMID 34262570, 2021). "To date, CD4+ and CD8+ T cells capable of co-producing IFN-γ, TNF-α and IL-2 (namely multifunctional CD4+ and CD8+ T cells) have been considered to be important for controlling various viral infections." (PMID 33142799, 2020). "Conversely, previous studies on viral infections in swine have shown that the CD4+ Tcm subset was capable of IFN-γ, TNF-α and/or IL-2 production." (PMID 33584671, 2020). "In mouse models of viral infections, CD27 was assessed as the key factor in directing the autocrine production of IL-2 that is required for the long-term survival of CD8+ T cells in nonlymphoid tissues." (PMID 31623665, 2019). "Many studies showed that IL-2, IFN-γ, and TNF-α are involved in the elimination of viral infection through modulating Th1 pattern and inflammatory responses." (PMID 31749917, 2019).
viral infection (continued). "Cytokines including GM-CSF, IL-2, IL-1β, TNF-α, IFN-γ, and IL-10 are key molecules that regulate innate and adaptive immune responses to viral infection." (PMID 31412594, 2019). "We demonstrated that BG induces the production of IL-2 and IFN-γ to amplify immune function, restrict viral replication, and euthanize virus-infected host cells upon viral infection." (PMID 31412594, 2019). "More specifically, our data shown that Arl4d interferes with signal transduction via the PI3K/Akt axis, leading to inhibition of cytokine production (IL-2) and suppression of SLEC development during viral infection." (PMID 30382149, 2018). "IL-12 and IL-18 secreted during viral infections by e.g., dendritic cells induce potent NK cell IFN-γ production and cytotoxicity, in particular in combination, and synergistically augment IL-2 and IL-15–induced NK cell activation." (PMID 30546366, 2018). "The increase in the spread of type I IFN changes the relative distributions pattern of IL-2 and IFN, so that the resulting alteration in the cytokine signalling reduces the clonal expansion and increases the overall level of the virus infection." (PMID 28681703, 2017). "Virus infection led to upregulation of CD25 on the Teffs, rendering them sensitive towards IL2 Ab Cx." (PMID 27886209, 2016). "The activation of PRRs induces the expression of cytokines and antiviral proteins, including IL-1β, IL-2, TNF-α, MX, and OAS, which alert the immune system to viral infection." (PMID 26005441, 2015). "Intriguingly, Treg cells appear to play a central role in anti-viral effector CD4 T cell fate decisions during viral infections due to their production of TGF-β and ability to consume IL-2." (PMID 25569154, 2015). "CD103+CD8+ T cells also contribute to protecting the human lung against viral infection by producing IFN-γ and other Th1 cytokines, such as IL-2." (PMID 25651850, 2015). "Bacterial etiology of infection was associated with significantly (P < 0.001) elevated serum concentrations of IL-1Ra, IL-2, IL-6, and TNF-α in comparison to levels observed in the sera of patients with viral infections." (PMID 23690657, 2013). "The concentrations of IL-1Ra, IL-2, IL-6, and TNF-α were significantly higher with the sera from the patients with bacterial infections than the sera from the patients with viral infections or the controls." (PMID 23690657, 2013). "Together, the behavior of these genes is consistent with an upregulation of immunosuppressive signals, compounded by the lack of factors that lead to the development of adaptive immune response such as production of IL2 and IL4 following virus infection." (PMID 23638192, 2013). "In a recent report, it was shown that in HIV-infected patients, control of viral infection required the presence of both IFN-γ and IL-2 producing T-cells." (PMID 22848556, 2012). "Cell proliferation and IL-2 and IFN-γ production of PBMC play important roles against bacterial and viral infection." (PMID 19633608, 2009). "The antigen-specific mCD4+ T cells clustered in areas associated with interferon gamma (IFN-γ), tumor necrosis factor (TNF), and interleukin-2 (IL-2) expression, which are the signature cytokines of the type 1 T helper (TH1) cells typically induced during viral infections." (PMID 40124502, 2025). "CD44+CD4+ and CD44+CD8+ T cells can secrete IL-2 and IFN-γ, with CD8+T cells potentially promoting activation of CD4+T cells through cytokine secretion, thereby exerting anti-infective effects against viral infections, intracellular bacteria, parasites, etc.." (PMID 40266142, 2025). "IL-2, IL-6, IL-17A, and IFN-γ are common immune factors in viral infections." (PMID 40872344, 2025). "None of the patients treated with IL‐2 developed Grade II–IV aGVHD, and the number of viral infections was significantly lower in the IL‐2 group than in the comparator group." (PMID 40391196, 2025).
viral infection (continued). "Selective Treg expansion can also be achieved using anti-IL-2 monoclonal antibodies (e.g., IL-2/JES6-1 complexes), which increase Treg/Teff ratios and alleviating inflammation, offering a precise means to correct immune dysregulation in viral infections." (PMID 40806563, 2025). "Since DC-derived IL-2 can stimulate the activation of T cells, it is possible that the increased IL-2 produced by PEP-null CRISPR and PEP-R619W DCs may be a contributing factor to the enhanced T-cell function observed during viral infection." (PMID 41208109, 2025). "IL-2 is chiefly synthesized via CD4+ T cellsafterwards antigen or mitogen stimulation and is also a cytokine with pleiotropiceffects, which takepart in the immune response and protection against viral infection." (PMID 40961276, 2025). "Viral infections necessitating hospitalization comprised viremia with CMV (N=53 in total; 30 in the ATG and 23 in the IL-2 RA group) and BKV (N=18 in total; 11 in the ATG and 7 in the IL-2 RA group)." (PMID 39606231, 2024). "Considering the high IgG2a/IgG1 ratio and the clear induction of HA specific T cells that produce IL-2 and IFN-γ, we conclude that our HA sa-mRNA vaccines induced a Th1-skewed response, favoring the elimination of viral infections." (PMID 39097672, 2024). "Excessive IL‐2 signalling could drive CD8+ T cells‐mediated tissue immunopathology, as seen in viral infections." (PMID 37720629, 2023). "Thus, IL-2 enhanced the magnitude of HIV replication in TFH, TFH survival, and particularly GFP+ TFH survival in both CXCR4-tropic and CCR5-tropic virus infection." (PMID 36420277, 2022). "During some viral infectious diseases, exhausted CD4+ Tcells reveal diminished proliferative capability and lack of multifunctional cytokine response, particularly decreased production of IL‐2, which results in disease progression." (PMID 34499819, 2021). "In systemic viral infection such as the LCMV model, overwhelmingly activated CD8+ T cells may sequester IL-2 from TREG cells." (PMID 34618873, 2021). "In our experiments, using transgenic ovalbumin expressing VSV, we demonstrate that without miR-155, T helper cells fail to expand during viral infection and are incapable of producing significant amounts of IL-2 and IFN-γ." (PMID 31275315, 2019). "We found that IL-2 levels were significantly lower in the HPV16+ group indicating that the local immune response failed to be further stimulated by virus infection." (PMID 31183395, 2019). "Recombinant IL-2 could enhance T cell survival, reverse T cell anergy, and maintain virus-specific CD8+ T cell numbers and function during persistent viral infection, such as HIV, simian immunodeficiency virus (SIV), and LCMV." (PMID 31632413, 2019). "Taken together, these results suggest that NK cells by IL-2 or viral infection can express isoforms of NKp46 lacking the D1 Ig-like domain, and NK cells expressing these domain-deficient receptors exhibit increased functional capacity." (PMID 28424697, 2017). "Because it has been suggested that cells simultaneously producing IFN-γ, IL-2, and TNF-α may provide optimal effector function and protection against viral infections, we defined the proportions of bifunctional cells in our immunized animals." (PMID 27183611, 2016). "Some pro-inflammatory cytokines induced during infection, such as IL-12, IFN-γ, IFN-αβ, and IL-2, promote Th1 differentiation; however, the signals required for Tfh differentiation during viral infection have not been as well characterized." (PMID 25569154, 2015). "Under specific conditions, for example, in response to viral infection, MSC produce also IL-2." (PMID 24876666, 2014). "While CD8+ T cell responses during acute viral infections were relatively independent of IL-2, the development of protective CD8+ T cell memory responses required IL-2 exposure during priming." (PMID 22279573, 2012).
viral infection (continued). "This magnification of TH1 associated cytokines and TNF-α is significant, as co-production of IFN-γ, IL-2, and TNF-α on polyfunctional antigen-specific T-cells has been shown to be the strongest criteria for predicting vaccine-elicited T-cell mediated protection against viral infection." (PMID 34603303, 2021). "Typically, CD4+ T cells secrete IL-2 and IFN-γ but chronic viral infections can significantly alter their cytokine profile to resemble those of their CD8+ counterparts with upregulation of programmed cell death protein 1 (PD-1) and downregulation of IL-2 and IFN-γ." (PMID 33172001, 2020). "Furthermore, we also evaluated the influence of PA on the production of interferon-γ (IFN-γ) and interleukin 2 (IL-2) in mice with or without PR8 virus infection." (PMID 31870450, 2019). "Additionally, the interleukin-2 (IL-2)-mTORC1 signaling axis promotes TH1 but inhibits TFH cell differentiation to orchestrate the reciprocal balance between TH1 and TFH cell fates during acute viral infection." (PMID 29875775, 2018). "To better understand counter-regulation of Treg cells by IL-2 and IL-21 in the absence of confounding virus dynamics, we delivered the IL-21 gene by hydrodynamic injection to IL-2ic treated mice in the absence of viral infection." (PMID 23696736, 2013). "While we observe minor decreases in the proportion of memory CD8 T cells in lymph nodes of mice lacking help, we find that these cells are not impaired in production of IFN-γ, TNF-α, or IL-2, as has been demonstrated for helpless T cells in viral infection models." (PMID 22046294, 2011). "In vivo efficacy studies revealed that a single low dose of IL-2 or IL-4-bearing CYT-IVAC is superior at providing protection against lethal influenza challenge in a mouse model and provides a more balanced Th1/Th2 humoral immune response, similar to live virus infections." (PMID 19393093, 2009). "Therefore, it is vital to mention that a T cell response is essential in viral infections, and in this sense, we analyzed whether the presence of the RBD protein can induce activation and cytokine production related to T lymphocytes, as well as IL-2 and IFN-γ." (PMID 38140191, 2023). "Moreover, we have shown that in vitro activation of 4-1BB-costimulated CAR4 T cells upregulates IL-2 and IL-21, which are cytokines that augment the function of CD8+ T cells during viral infection, and thus may have contributed to the sustained CAR8 T cell response that we observed in vivo." (PMID 32454027, 2020). "Using both mouse and human systems, the thymic effects of systemic immunostimulatory regimens, such as high dose IL-2 (HD IL-2) with or without agonistic anti-CD40 mAbs and acute primary viral infection, were investigated." (PMID 39315105, 2024). "The sorted cells were subsequently cultured with an integrase inhibitor, preventing new rounds of virus infection, and treated with 100 U/mL of IFN (α, β, ε, ω, λ1 or λ3) in the presence or absence of anti-CD3/CD28+IL-7+IL-2." (PMID 32109259, 2020). "The contribution of IL-2 was low, suggesting that IL-2 producing memory T cells were dispensable in BCG infection, unlike in certain viral infections." (PMID 30546366, 2018). "Indeed, the lack of Arl4d results in higher IL-2 production and more pronounced effector cell development, as measured by an increase in KLRG1posCD127neg short-lived effector CD8 T cells during viral infection in vivo." (PMID 30382149, 2018).
systemic lupus erythematosus (177 papers, 2006 to 2026). An autoimmune multi-organ disease typically associated with vasculopathy and autoantibody production. "Treatment of MRL/lpr lupus-prone mice with IL-2-recombinant adeno-associated virus led to amelioration of lupus-related skin, lung and renal pathological lesions, accompanied by a significant reduction of IL-17-producing DNTC and increase in Treg number." (PMID 35326431, 2022). "In NZB/NZW F1 lupus-prone mice, IL-2 deficiency was shown to induce hyperactivity of conventional T cells, and low Treg to conventional T cell ratio." (PMID 35326431, 2022). "Reduced Treg numbers have been positively linked with disease activity in SLE patients and in lupus-prone mice and were associated with an impaired capacity of T cells to produce IL-2." (PMID 35626662, 2022). "IL-2 is discussed to be rather protective than pathogenic in SLE because the acquired IL-2 deficiency is a crucial general event in the pathogenesis of lupus and mainly leads to a disorder of the homeostasis of regulatory T cells." (PMID 32441253, 2020). "An acquired deficiency of IL-2 profoundly affects Treg biology in lupus-prone individuals and significantly contributes to the immune pathogenesis of SLE." (PMID 31614462, 2019). "Treatment of MRL/lpr lupus-prone mice with an IL-2-expressing recombinant adeno-associated virus resulted in reduced pathology, decreased DN cell numbers and increased Treg cell numbers." (PMID 29868033, 2018). "Evidence indicates that lupus is characterized by deficiencies in both IL-2 and TGF-β production." (PMID 41368646, 2025). "Whether IL-2 defects primarily predispose to lupus pathogenesis, or are secondary to disease activity, remains a major question for the field." (PMID 38915570, 2024). "The fact that D2 T cells have a major impairment in in vitro and ex vivo IL-2 production supports the hypothesis that a primary IL-2 defect can predispose to lupus pathogenesis." (PMID 38915570, 2024). "Interestingly, T-bet-related age-associated B cells (ABCs) and low-dose IL-2 treatment in lupus were emergently discussed as well." (PMID 38164134, 2023). "The decrease in IL-2 level was found to be associated with a depleted Treg cell population, and its reversibility by IL-2 therapy provides important reasons for the treatment of lupus." (PMID 37771588, 2023). "Likewise, lupus-prone MRL/lpr mice also featured IL-2 deficiency and restored IL-2 production ameliorated GN." (PMID 33496881, 2021). "In conclusion, the phenotype of intrarenal Treg together with the progressive homeostatic Treg/Tcon imbalance suggests that a deficiency of IL-2 is also present in the inflamed kidneys of lupus-prone mice and such shortage of IL-2 occurs early during the course of LN." (PMID 31614462, 2019). "Genome-wide association studies have identified the locus encoding Il21 and Il2 as a risk factor for autoimmune diseases such as systemic lupus erythematosus (SLE), type 1 diabetes, inflammatory bowel disease, coeliac disease, psoriasis and psoriatic arthritis." (PMID 31557986, 2016). "The pre-existing defect in IL-2 production seen in otherwise normal D2 mice supports a disease model that some lupus-predisposed individuals may have pre-existing defects in T cell IL-2 production that may go undetected, particularly in the setting of a normal innate immune response." (PMID 38915570, 2024). "In this retrospective study, Low-dose IL-2 therapy was found to be associated with the reduced incidence of infection in systemic lupus erythematosus (SLE) patients." (PMID 34618873, 2021). "An acquired deficiency of interleukin-2 (IL-2) and related disturbances in regulatory T cell (Treg) homeostasis play an important role in the pathogenesis of systemic lupus erythematosus (SLE)." (PMID 31614462, 2019). "IL-2 mutein candidates have been tested in clinical trials for autoimmune conditions such as systemic lupus erythematosus." (PMID 40671830, 2025).